CD36 (CD36 molecule (CD36 blood group))
Diseases named in the same sentence as CD36 in open-access papers (continued):
Sharing a sentence is not in itself a finding about the gene and the disease.
Hepatic steatosis (continued). "The excess lipid uptake mediated through FATP and CD36 contributes to hepatic steatosis in NAFLD." (PMID 36148775, 2022). "We discovered the novel mechanism that Alisol B upregulated the disrupted expression of RARα and then decreased CD36 expression via RARα-HNF4α-PPARγ transcriptional cascade, which further alleviated hepatic steatosis, oxidative stress, inflammation, and fibrosis in the liver of NASH mice." (PMID 35745142, 2022). "The CD36 fatty acid transporter is central in the pathogenesis of hepatic steatosis." (PMID 36246929, 2022). "The activation of CD36 promotes uptake of free fatty acids from the circulatory system and may be involved in hepatic steatosis." (PMID 36111293, 2022). "The decrease in PPARγ and CD36 levels suggests a protective response against hepatic steatosis." (PMID 35276938, 2022). "Hepatic expression of CD36 is typically low although it increases with fatty liver disease." (PMID 34327606, 2022). "Furthermore, we found that starvation-induced hepatic steatosis in zebrafish larvae can be rescued by targeting the knockout cd36 gene." (PMID 33513687, 2021). "Moreover, the results revealed a novel association between the central nervous system and liver, whereby PRL/PRLR improved hepatic steatosis via the CD36 pathway." (PMID 33716958, 2021). "Moreover, it has been reported, that hepatic extracellular galectin-3 is upregulated in NASH and its inhibition in mice fed with a HFD, reduced hepatic CD36 expression, the accumulation of lipids and hepatic steatosis." (PMID 34957117, 2021). "Prolactin inhibits hepatic steatosis by the CD36 pathway and reduces SCD1 gene expression." (PMID 33849585, 2021). "Our findings demonstrate a protective role of miR-100 in high fat diet induced metabolic syndrome and liver steatosis, partially mediated by the direct repression of CD36 and attenuation of hepatic lipid storage, implicating miR-100 as a possible therapeutic target in liver steatosis." (PMID 34488621, 2021). "CD36 plays an important role in liver lipid homeostasis, lipophagy and autophagy, and its levels increase in hepatocytes exposed to high-fat diets as well as in hepatic steatosis and NAFLD." (PMID 34957117, 2021). "Reports on the elevated expression of FAT/CD36 in high-fat, diet-induced fatty liver also exist." (PMID 33670590, 2021). "Interestingly, deletion of Cd36 inhibited the effect of LXR agonists on hepatic lipid accumulation, indicating that this fatty acid translocase is crucial for hepatic steatosis onset induced by nuclear receptors." (PMID 32978374, 2020). "The FA transporter CD36 mediates FA uptake and plays an important role in hepatic steatosis." (PMID 32807074, 2020). "In order to investigate whether intermittent hypoxia (IH), one of the main features of OSA, contributes to liver steatosis and to the increase of CD36 expression observed in OSA patients, a mouse experimental model of OSA was used." (PMID 32850919, 2020). "In fact, the induction of CD36 translocation to the plasma membrane of the hepatocytes may be a determining factor in the physiopathology of hepatic steatosis in NAFLD patients." (PMID 32978374, 2020). "Upregulation of ACC and FASN expression may have contributed to the initial increase in hepatic adiposity in rats fed an ND, and activation of CD36 expression was responsible for the development of hepatic steatosis in rats fed an HFD." (PMID 32807074, 2020). "It has been reported that CD36 expression is significantly upregulated in hepatic tissues of NAFLD patients and overexpression of CD36 in the liver increases TG accumulation and causes hepatic steatosis progression." (PMID 32733940, 2020).
Hepatic steatosis (continued). "Also, improvement of hepatic steatosis by CD36 downregulation in a murine model of NAFLD was reported for another FXR agonist, GW4064, which is also an inhibitor in our phenotypic model, with similar potency to OCA, albeit lower efficacy (data not shown)." (PMID 30254132, 2018). "Moreover, CD36 plays an active role in fatty acid uptake and has significant effects on hepatic steatosis and insulin sensitivity." (PMID 30037134, 2018). "Of note, CD36 was increased by 2-fold and histopathology revealed hepatic steatosis." (PMID 29296203, 2017). "CD36, the class B scavenger receptor, has been reported to facilitate the uptake of long chain fatty acids by endothelial cells as well as macrophages, and plays a role in hepatic steatosis induced by feeding a HFD." (PMID 27172901, 2016). "Additionally, another study demonstrated that CD36 mRNA levels increased concomitantly with hepatic TG content in a number of animal models of fatty liver." (PMID 25310357, 2014). "This may have contributed to a strong lipogenic drive with age, explaining not only the increased membrane abundance of CD36 but also the increased hepatic steatosis following HF-feeding in middle-aged mice." (PMID 24751397, 2014). "CD36 also has been considered to contribute to the progression of hepatic steatosis." (PMID 24016701, 2013). "In addition to their control of lipid metabolism, several of these lipogenic genes, including Cidea, Cidec, and Cd36, play a critical role in regulating the development of hepatic steatosis and insulin sensitivity." (PMID 23505504, 2013). "Such change in CD36 distribution might be involved in increased intrahepatic triglyceride content, and subsequently hepatic steatosis." (PMID 24016701, 2013). "Excessive fatty acid uptake mediated by CD36 plays an important role in hepatic steatosis." (PMID 23448206, 2013). "We then investigated whether hydrogen could modulate signaling pathways after palmitate overload as well as CD36 expression after hydrogen treatment in this cell culture model of hepatic steatosis." (PMID 23448206, 2013). "CD36, a multiligand scavenger receptor present on the surface of a number of cell types, may contribute to hepatic steatosis by facilitating the high-affinity uptake of fatty acids from the circulation." (PMID 22187655, 2012). "Furthermore, a previous study showed not only a significant increase in hepatic Cd36 expression in mice fed trans-10, cis-12-CLA but also a significant association between Cd36 expression and the degree of hepatic steatosis." (PMID 22988513, 2012). "PXR may also promote hepatic steatosis by increasing the expression of CD36 directly or indirectly through the PXR-mediated activation of PPARγ." (PMID 22187655, 2012). "However, this is in contrast with studies showing hepatic overexpression of Pparγ in mouse models lead to adipogenic lipogenesis and that Pparγ and Cd36 are upregulated during hepatic steatosis." (PMID 23236485, 2012). "It has also been reported that the development of fatty liver was prevented in CD36 null mice." (PMID 22363472, 2012). "Notably, the glycerophospholipid dysregulation aligns with recent mechanistic studies where lipid metabolism perturbations (specifically CD36-mediated pathways) directly drive hepatic steatosis pathogenesis, as demonstrated in CRISPR-Cas9-based NAFLD interventions targeting Rubicon." (PMID 40870694, 2025). "In addition, Cd36 and Lpl upregulation in KD-TN versus KD-RT may enhance lipid storage, further contributing to hepatic steatosis and metabolic stress." (PMID 40864559, 2025). "Combined with previous research reavealing that oxidative stress is responsiple for the upregulation of CD36 and DGAT2, it is considered that probiotics could provide a certain degree of protection against VPA-caused liver steatosis through the alleviation of oxidative stress." (PMID 37971986, 2023).
Hepatic steatosis (continued). "Finally, a hepatic knockout mouse for Cd36 gene (Cd36KO) revealed the attenuation of hepatic steatosis, including a decreased mRNA and protein expression of different lipogenic genes such as SREBP1c, suggesting that Cd36 could have a pivotal role in DNL." (PMID 37628929, 2023). "We have been able to demonstrate that transgenic mice overexpressing the human ApoD will develop a non-inflammatory hepatic steatosis caused by an increase in fatty acid uptake due to increased hepatic CD36 expression, altered ARA metabolism, and amelioration of the ω-6/ω-3 ratio." (PMID 37237893, 2023). "Interestingly, there are interactions between CD36 and the intracellular processing of FAs, since the overexpression of CD36 results not only in increased FA absorption, but also in decreased β-oxidation and autophagy, contributing to the development of fatty liver disease." (PMID 37628929, 2023). "Therefore, the down-regulation of CD36 may be an important mechanism contributing to the effect of Ala-Gln to attenuate hepatic steatosis." (PMID 36145172, 2022). "Besides, overexpression of CD36 increases hepatic uptake of fatty acids in high-fat diet-induced obese mice, whereas knockdown of CD36 decreases lipid accumulation in both diet-induced and genetic steatosis, suggesting that CD36 is critical in the development of hepatic steatosis." (PMID 35625757, 2022). "Therefore, OTA induces hepatic steatosis via PPARγ-CD36 axis, suggesting that OTA has an impact on liver lipid metabolism and may contribute to the development of metabolic diseases." (PMID 34822586, 2021). "Therefore, the treatment of GH treatment could attenuate hepatic steatosis and inflammation with downregulation of CD36 expression in hyperlipidemic condition." (PMID 33209195, 2020). "Thus, we speculate that forced expression of NR2F6 could promote liver steatosis by specifically enhancing FFA uptake through CD36." (PMID 33173745, 2020). "Indeed, a high liver content of Cer(d18:1/22:0) and Cer(d18:1/24:0) might prevent hepatic steatosis under fat overload conditions by reducing peroxisome proliferator-activated receptor γ2 content and, as a consequence, reducing CD36 and FSP27 gene expression." (PMID 32560216, 2020). "Besides the genes related to fatty liver, these findings may be linked to the ancestral Amerindian-derived risk alleles of the taste receptors TAS1R2, CD36, and TAS2R38 that are known to alter food preferences." (PMID 30608932, 2019). "Similarly, we also observed the attenuated hepatic steatosis and the decrease of SREBP1c, Pparγ, Scd1 and Cd36 involved in lipogenesis and lipid uptake, and increase of Cpt1, Acat and Echs1 involved in fatty acid oxidation in the liver of mice fed HFD and hemin." (PMID 28933767, 2017). "In addition, forced expression of Cd36 in livers of normal fed, nonmetabolically challenged mice caused hepatic steatosis, and an age-related increase in hepatic CD36 expression is associated with increased susceptibility to NAFLD." (PMID 26085100, 2015). "Hence, ezetimibe may ameliorate hepatic insulin resistance in addition to dyslipidemia and hepatic steatosis, partly via a pathway involving CD36 in high-fat diet-induced B6 mouse models of NAFLD." (PMID 25310357, 2014). "Conversely, forced expression of CD36 in liver causes hepatic steatosis in the absence of HFD." (PMID 23448206, 2013). "Conversely, forced expression of hepatic CD36 without a HFD caused hepatic steatosis." (PMID 22363472, 2012). "Studies have shown that CD36 (a fatty acid transport protein) plays a pivotal role in MAFLD, and modulating its expression directly affects hepatic steatosis in the liver." (PMID 40110132, 2025). "CD36 silencing significantly attenuated HUA-induced TG accumulation, confirming the critical role of CD36 in UA-driven hepatic steatosis." (PMID 41391771, 2025).
Hepatic steatosis (continued). "As expected, LG treatment significantly and dose-dependently ameliorated DXM-induced fatty liver and abrogated DXM-induced upregulation of FASN and CD36 protein expression." (PMID 39820544, 2025). "At the mRNA and protein levels, CD36 was also upregulated in patients with NAFLD and was significantly related to the extent of fatty liver." (PMID 39774047, 2025). "Our results suggest that the beneficial effects of LG on DXM-induced fatty liver are mediated, at least in part, by AMPK activation, which in turn downregulates FASN and CD36 expression." (PMID 39820544, 2025). "SSO reduces intestinal fatty acid absorption by reducing the inhibition of intestinal CD36 expression, followed by decreased TG and FFA levels, which attenuates HFD-induced fatty liver." (PMID 37305546, 2023). "Free fatty acid uptake by hepatic fatty acid transporters such as CD36 and FATP5 promotes hepatic steatosis by increasing PPAR-γ." (PMID 37007480, 2023). "Important to note is that increased CD36 and FASN expression has shown to be related to increased hepatic steatosis." (PMID 36946061, 2023). "CD36 can also interact with insulin-induced gene-2 (INSIG2) to increase the level of SREBP1 synthesis, promote de novo synthesis of fatty acid and induce hepatic steatosis." (PMID 36594091, 2023). "Extensive research has been conducted to investigate the role of CD36 in the development of MASLD, as its expression in the liver directly influences the occurrence of hepatic steatosis." (PMID 38089874, 2023). "PCSK9 knockout (KO) mice develop severe hepatic steatosis when fed a high-fat diet, since PCSK9 reduces the expression of fatty acid translocase also known as CD36, a scavenger receptor for fatty acid uptake and the main driver of their uptake in the liver." (PMID 35900635, 2022). "Hepatic knockdown of PPARγ in mice leads to resistance to high-fat-diet-induced hepatic steatosis and the decrease of genes involved in lipogenesis (SREBP1 and SCD1) and FA transporters regulated by PPARγ (CD36)." (PMID 35276938, 2022). "At the molecular level, we have discovered metabolic pathways by which Dyrk1b induces hepatic steatosis (a) by activating mTORC2 and augmenting DNL and (b) by upregulating Fabp1 and CD36 and increasing FA influx into the liver." (PMID 34855620, 2022). "Deleting FGF21 from LSD1-LKO liver partially reversed the improved hepatic steatosis, likely due to the FGF21-dependent alteration of lipid uptake (Cd36) and secretion (ApoB, ApoA4, and ApoA5)." (PMID 34314389, 2021). "In obese rats, CD36 mRNA expression is positively related to the IHTG level and liver steatosis severity." (PMID 34512784, 2021). "Corticosterone, administered to rodent models to increase basal glucocorticoids levels, also induces an increase in Cluster Determinant 36 (CD36) expression that facilitates fatty-acid uptake, favoring the progression of hepatic steatosis." (PMID 34067649, 2021). "Abundant studies have demonstrated that the expression of hepatic CD36 is increased during the development of NAFLD with the capability of promoting hepatic fatty acids uptake, thus resulting in the enhancement of hepatic steatosis." (PMID 34712137, 2021). "A previous report suggested that CD36 is also a target gene of LXRα, while LXR agonist-induced hepatic steatosis was largely abolished in CD36 knockout mice." (PMID 32443660, 2020). "Overall, similar to CD36, FABP1 overexpression can lead to abnormal liver functions such as dyslipidemia and hepatic steatosis." (PMID 32733940, 2020). "CD36 functions as a transporter mediating liver long-chain FFA uptake and esterification, which regulates the development of hepatic steatosis." (PMID 28770225, 2017).
Hepatic steatosis (continued). "At the molecular level, losartan only significantly decreased FAT/CD36 and FAS mRNA together with UCP2 mRNA, but these effects appear insufficient to impact hepatic steatosis or ATP content respectively." (PMID 28231800, 2017). "Expressions of fatty liver disease-related genes in liver were analyzed by qRT-PCR, in which FASN and CD36 were down-regulated according to the increasing dose of KIOM2012H in a similar way to HepG2 cells." (PMID 25849950, 2015). "The expression level of CD36 is very low in normal liver tissues, but is drastically increased in the liver tissues of high-fat diet (HFD)-induced fatty liver mice and those of human NAFLD." (PMID 23448206, 2013). "Notably, previous studies have shown that liver-specific CD36 knockout in HFD-fed mice significantly reduces hepatic FFA uptake and alleviates hepatic steatosis." (PMID 41391771, 2025). "Palmitoylation inhibition disrupts CD36-COPII colocalization and improves hepatic steatosis." (PMID 41306774, 2025). "Overall, CD36 expression in the liver increased significantly in both patients with NAFLD and mouse models; in parallel with CD36 expression, fatty acid uptake increased significantly, indicating that CD36 is closely related to the development of fatty liver." (PMID 39774047, 2025). "Interestingly, in CD36-overexpressing transgenic mice, an attenuation of HFD-induced hepatic steatosis was observed." (PMID 38671851, 2024). "This suggests that there may be other mechanisms, other that KLF2-induced upregulation of CD36, involved in KLF2-induced liver steatosis." (PMID 37949368, 2024). "Additionally, by inhibiting the FAS and Nrf2 pathways, it decreases the expression of CD36, SREBP1c, and the small heterodimer partner (SHP), which decreases hepatic steatosis." (PMID 39061866, 2024). "Thus, it suggests that the elevated CD36 and DGAT2 levels contribute to VPA-induced liver steatosis, which is further supported by the improved lipid deposit and the decreased CD36/ DGAT2 levels after probiotics treatment." (PMID 37971986, 2023). "It is tempting to speculate that the elevated hepatic Th17 response of HFD-fed CD11cΔLKB1 mice contributes to worsened hepatic steatosis and insulin resistance through TRAF6-C/EBPα–mediated enhanced Cd36 expression." (PMID 37140993, 2023). "CD36, an AhR target gene that promotes FFA translocation into the liver, was reduced in HFD-fed CadKO females, suggesting a mechanism for protection from hepatic steatosis." (PMID 37443781, 2023). "Recent studies show that increased CD36 levels are accompanied with elevated FFA uptake and TG storage, while hepatocyte-specific Cd36 deletion protects against HFD-induced liver steatosis, thus this protein might have a crucial role in NAFLD pathology." (PMID 37004042, 2023). "In this study, our data showed that FTZ alleviated the expression of PPAR-γ and CD36 in livers from HFD-fed mice at least in part, which may impact the severity of hepatic steatosis as well as improve whole-body insulin sensitivity." (PMID 35784533, 2022). "CD36 is a multifunctional signaling molecule with several ligands, including long-chain FFA, HDL, LDL, and VLDL, and plays a pivotal role not only in adipose inflammation but also in liver steatosis." (PMID 34829968, 2021). "Moreover, synthesis of cluster of differentiation 36 (CD36) protein in the liver, which presumably lessened HFD-triggered hepatic steatosis in mice, was suppressed both in terms of protein and respective coding mRNA, when LTg mice are compared to WT mice." (PMID 34361079, 2021). "Moreover, pre-incubation of a CD36 inhibitor, sulfosuccinimidyl oleate (SSO), also reduced OTA-induced cellular TG accumulation, further confirming that OTA-induced hepatic steatosis was dependent on CD36." (PMID 34822586, 2021).